BRAFP1 (BRAF pseudogene 1)
Synonyms: BRAF2; BRAFPS2
Gene: Unprocessed pseudogene on chromosome X (75,582,676 to 75,585,506, forward strand). Ensembl gene ENSG00000224775.
Diseases named in the same sentence as BRAFP1 in open-access papers:
BRAFP1 is named in the same sentence as 12 diseases in open-access papers, as found by Europe PMC text mining. Sharing a sentence is not in itself a finding about the gene and the disease. The quoted sentences say what the papers report.
lymphoma (3 papers, 2017 to 2022). A malignant (clonal) proliferation of B- lymphocytes or T- lymphocytes which involves the lymph nodes, bone marrow and/or extranodal sites. "The pseudogene BRAFP1 regulates BRAF expression through functions as a ceRNA and competitive binding of miR-30a, miR-182, miR-876, and miR-590, which finally Induces lymphoma in vivo." (PMID 28029651, 2017).
B cell lymphomas (2 papers, 2020 to 2022). "Overexpression of the oncogenic pseudogene BRAFP1 promotes the formation of human B-cell lymphomas through serving as a ceRNA of the parental gene BRAF." (PMID 35430805, 2022).
cancer (7 papers, 2015 to 2025). A tumor composed of atypical neoplastic, often pleomorphic cells that invade other tissues. "The pervasive dysregulation of pseudogenes across cancer types—with some functioning as tumor suppressors (e.g., PTENP1) and others as oncogenic drivers (e.g., KRASP1, BRAFP1)—highlights their importance as a novel class of cancer genes." (PMID 41473691, 2025). "Parallel to PTENP1, other pseudogenes like KRASP1 and BRAFP1 have been implicated in cancer pathogenesis through similar ceRNA mechanisms, with KRASP1 sponging miR‐143 and let‐7 family to protect KRAS mRNA and BRAFP1 enhancing oncogenic signaling by sequestering microRNAs that target BRAF." (PMID 41473691, 2025). "In addition, several transcriptional or genomic aberrations of BRAFP1 were frequently found in multiple human cancers, including B cell lymphomas." (PMID 26895108, 2016). "In addition, BRAFP1 genomic locus was found amplified in the vast majority of cancer types featured in TCGA, including DLBCL, where, as expected by ceRNA partners, BRAFP1 and BRAF expression levels show a positive correlation." (PMID 26442270, 2015). "Moreover, the human BRAF pseudogene (BRAFP1) has been recently found overexpressed in various tumor types, suggesting that it may contribute to cancer development." (PMID 26895108, 2016).
BRAFP1 also shares sentences with these, for which no sentence is quoted: tumor (4 papers); melanoma (2); clear cell renal carcinoma (1); diffuse large B-cell lymphoma (1); gastric cancer (1); lung carcinoma (1); metastatic melanoma (1); myeloma (1); prostate carcinoma (1).